TRPV1 (transient receptor potential cation channel subfamily V member 1)
Diseases named in the same sentence as TRPV1 in open-access papers (continued):
Sharing a sentence is not in itself a finding about the gene and the disease.
diabetic neuropathy (continued). "We have previously reported correlations of nerve growth factor (NGF), which regulates TRPV1 expression, with skin flare area in patients with diabetic neuropathy." (PMID 17683543, 2007). "In sensory neurons, TRPV1 serves as a major conduit for diabetic neuropathy." (PMID 41463571, 2025). "CB1R, CB2R, and TRPV1 channels are upregulated in the spinal cord and the DRGs of different models of neuropathic pain, such as diabetic neuropathy." (PMID 37745077, 2023). "It is reasonable to suggest that during diabetic neuropathy, rats tend to be more sensitive to modulation of TRPV1 activity and changes in TRPV1 expression may be involved in glutamatergic circuits, namely OFF cells." (PMID 37153792, 2023). "On the other hand, TRPV1 missense variants localized in transmembrane domains have been reported in diabetic neuropathy patients without pain, which highlights the need of functional variant validation before drawing a definite conclusion." (PMID 36430572, 2022). "These authors also published a distinct paper showing a similar profile of increased expression for TRPV1 in the DRG and spinal cord and the antinociceptive effect of i.t. injection of TRPV1 antagonists for mechanical allodynia in the painful diabetic neuropathy model in rats." (PMID 36670886, 2022). "Because there was no important difference in kcal/mol between 6-shogaol and the drug; therefore, it was noted that 6-shogaol could be developed as TRPV1 for the treatment of Painful Diabetic Neuropathy (PDN)." (PMID 34899343, 2021). "In addition, the capsaicin receptor TRPV1 can become up-regulated in hyperalgesia due to peripheral nerve injury and in some cases of diabetic neuropathy." (PMID 29953534, 2018). "Collectively, our data strongly suggest that phosphorylation of TRPV1 channels by these kinases may provide potential therapeutic targets to manage sensory abnormalities in diabetic neuropathy." (PMID 29474476, 2018). "However, the role of specific PKC isoform/s mediating the TRPV1 sensitization during the first phase of diabetic neuropathy is not well understood." (PMID 27721335, 2011). "Reduction of TRPV1 levels in nerve fibres in diabetic neuropathy skin may result from the known decrease of nerve growth factor (NGF) levels." (PMID 17521436, 2007). "Furthermore, animal experiments suggest that TRPV1 expression may be decreased in some patients, for example those with diabetic polyneuropathy." (PMID 38339399, 2024). "Interestingly, Facer and coworkers found TRPV1 to be reduced in diabetic neuropathy patients." (PMID 21468319, 2011). "However, the specific isoforms of PKC that may be involved in sensitization of TRPV1 during diabetic neuropathy remains unresolved." (PMID 27721335, 2011). "There is a strong link between TRPV1 and AGE–RAGE, confirmed by their involvement in diabetic neuropathy." (PMID 39337455, 2024). "Another study reported that ginger extract and its compounds attenuated hyperalgesia and allodynia in mice by reducing spinal TRPV1 and NR2B expression in a streptozotocin-induced mouse model of painful diabetic neuropathy." (PMID 34681836, 2021). "The current study agrees with previous observations showing that TRPV1 and TRPA1 channels play an important pronociceptive role in the painful diabetic neuropathy and extends these observations to TRPC channels." (PMID 30602386, 2019). "Several papers have reported potentiation of TRPV1 responses through PKC-mediated pathways, and PKC-potentiated TRPV1 responses have been shown to contribute to diabetic neuropathy." (PMID 16842630, 2006). "The finding indicates that modulation of endogenous CGRP may be an effective way to rebuild the loop of cross-enforcing mechanism between TRPV1 and CGRP in diabetic neuropathy and the enteral administration of capsaicin may be a safe and convenient way for the chronic intervention." (PMID 33462325, 2021).
glioma (31 papers, 2012 to 2026). A benign or malignant brain and spinal cord tumor that arises from glial cells (astrocytes, oligodendrocytes, ependymal cells). "TRPV1 is implicated in the capsaicin-induced p38 mitogen-activated protein kinase-dependent apoptosis of glioma cells in vitro." (PMID 34458247, 2021). "Here, we discuss the potential as biological markers of diagnosis and prognosis of TRPC6, TRPM8, TRPV4, or TRPV1/V2 being associated with glioma patient overall survival." (PMID 33928077, 2021). "Evaluation of TRPV1 variant transcripts was also performed in Human Normal Progenitor Cells (HNPCs; n = 3), in Glioma Stem-like Cells (GSCs; n = 4) and in differentiated GSCs (dGSCs; n = 4)." (PMID 27829230, 2016). "Moreover, in patient samples, the TRPV1 gene and protein expression were inversely correlated with glioma grading, and a near complete loss of TRPV1 expression was found in grade IV glioblastoma." (PMID 36768856, 2023). "The anti-tumorigenic functional role of TRPV1 in gliomas, suggested by its marked downregulation or loss in patients with the shortest overall survival, has been investigated and several findings highlighted a role of TRPV1 in the induction of apoptotic cell death signaling in gliomas." (PMID 33928077, 2021). "In particular, a study performed by Nabissi and coworkers has shown that GBM and glioma stem-like cells (GSC) selectively express the TRPV1 5′-untranslated region (5′UTR) variant three (TRPV1v3), one of the four variants resulting from alternative first exon splicing." (PMID 33928077, 2021). "Moreover, the correlation between the expression of a most stable TRPV1 variant-3 (TRPV1v3) in GSCs and survival suggests an important role played by TRPV1 in glioma." (PMID 34440820, 2021). "Finally, TRPV1 mRNA and protein expression inversely correlated with glioma grading, with a marked loss of TRPV1 expression in the majority of grade IV glioblastoma tissues." (PMID 22523714, 2012). "Moreover, this hypothesis was supported by the analysis in grade I-III gliomas, where we found that TRPV1 variant expression levels were inversely correlated to the glioma grade." (PMID 27829230, 2016). "The antitumor effects of CBD appear to be mediated by transient receptor potential cation channels (TRPVs) in endometrial cancer, glioma, bladder cancer, and myeloma, with TRPV1, TRPV2, and TRPV4 playing key roles in activating apoptosis." (PMID 40006844, 2025). "In human anaplastic thyroid carcinoma and glioma cells, capsaicin-induced Ca2+ influx through TRPV1 has been shown to initiate p38 MAPK signaling and mitochondrial apoptosis, effects abrogated by TRPV1 antagonists." (PMID 40808836, 2025). "The results of the spheroid model showed that the genes TRPC3, TRPC4, TRPC5, and TRPV1 were upregulated in glioma cells either wild‐type isocitrate dehydrogenase 1 (IDH1) or the IDH1 R132H mutant, with or without NaCl treatment." (PMID 39189437, 2024). "As predicted by this tissue distribution, TRPV1 expression has been described in carcinomas, melanomas, gliomas, and hematological malignancies." (PMID 37240443, 2023). "For example, the release of endovanilloids by NPCs activates the transient receptor potential vanilloid subfamily member-1 (TRPV1) on glioblastoma cells, thereby reducing glioma expansion and prolonging survival time." (PMID 36768856, 2023). "First, we found up-regulated CNR1, GPR55, and TRPV1 expression in glioma patient-derived tissue samples and cell lines compared with non-malignant brain samples." (PMID 36497400, 2022). "Overexpression of TRPV1 has been reported in solid cancers, including glioma and human tongue epithelium cancer, whereas lower expression was reported in urothelial cancer." (PMID 35477804, 2022). "In this study, in contrast to CNR1 and GPR55, TRPV1 mRNA negatively correlated with glioma grade and positively correlated with overall survival." (PMID 36497400, 2022).
glioma (continued). "The focus of the present research was to first determine CB1/CNR1, GPR55, and TRPV1 gene expression in glioma samples and in differentiated GBM cells and GSCs." (PMID 36497400, 2022). "In contrast, the ionotropic receptor TRPV1 gene was significantly downregulated with glioma progression, possibly indicating its tumour suppressor role." (PMID 36497400, 2022). "Significant correlations were only found between survival and TRPV1 expression: that lower TRPV1 mRNA expression correlates with shorter glioma patient survival." (PMID 36497400, 2022). "Although renowned as a nociceptive receptor, TRPV1 expression has been detected in many cancers, including glioma, breast cancer, prostate cancer, colon adenocarcinoma, and pancreatic cancer." (PMID 35477804, 2022). "More importantly, NPCs migrate into high-grade astrocytomas to reduce glioma expansion and prolong survival by release of fatty acid ethanolamides by triggering a TRPV1-dependent astrocytoma death, via the activation of ATF3 of the ER stress pathway." (PMID 34440820, 2021). "For example, capsaicin induces caspase activation and apoptosis through increased Ca2+ influx in glioma cells; these events were markedly inhibited by TRPV1 antagonist." (PMID 32604833, 2020). "Capsaicin, the best-known TRPV1 agonist, stimulates apoptosis in pancreatic, urothelial, and renal cancer cells, and gliomas." (PMID 32604833, 2020). "Accordingly, AEA in the range of 0.01 to 10 μM was found to elicit an antiproliferative action on glioma cells via both cannabinoid receptors and TRPV1 by enhancing downstream oxidative stress and calpain activation." (PMID 31143113, 2019). "As such, AEA was found to induce apoptosis in neuroblastoma, lymphoma and cervical cancer cells and to inhibit glioma cell proliferation via TRPV1 activation." (PMID 31143113, 2019). "R(+)-methanandamide (10 μM) was shown to elicit apoptosis via a mechanism bypassing cannabinoid and TRPV1 activation in cervical and lung cancer as well as glioma cells." (PMID 31143113, 2019). "The TRPV1 channel, whose regulation was investigated in glioma, evidenced different expression patterns." (PMID 27829230, 2016). "As shown NB, NHA and glioma grade I samples expressed at different levels all the 5'UTR TRPV1 variant transcripts, while some samples resulted express the TRPV1 variants: grade II (10/12), III (12/20) and IV samples (38/40)." (PMID 27829230, 2016). "Herein, we investigated the role of the 5'UTR sequences in TRPV1 transcripts stability, regulation of translation, expression in glioma cells and tissues." (PMID 27829230, 2016). "In order to investigate the role of the 5'UTR in regulating mRNA stability, we measured the half-life of the TRPV1 5'UTR variant mRNAs, in U87 and U251 glioma cell lines." (PMID 27829230, 2016). "We have previously reported that TRPV1 is expressed in glioma tissues but not in epileptic brain tissues, with an inverse correlation between TRPV1 expression levels and pathological glioma grade." (PMID 27829230, 2016). "The effect of rapamycin and interferon-gamma in 5'UTR-regulating TRPV1 translation was determined by western blot analysis in glioma cell lines." (PMID 27829230, 2016). "We demonstrated that the 5'UTR influences the stability and translation efficacy of TRPV1 transcripts, and that TRPV1 variant three (TRPV1v3) was the most stable and the only variant expressed in GBM samples and in glioma stem-like cells." (PMID 27829230, 2016). "TRPV1 activation by capsaicin induced apoptosis of U373MG glioma cells, and involved rise of Ca2+ influx, p38MAPK activation, mitochondrial permeability transmembrane pore opening and transmembrane potential dissipation, and caspase-3 activation." (PMID 22523714, 2012). "Notably, we observed among the articles included in this study that CBD was able to interact mainly with TRPVS receptors, as in endometrial cancer (TRPV1), glioma (TRPV2 and TRPV4), bladder cancer (TRPV2), and myeloma (TRPV)." (PMID 40006844, 2025).
glioma (continued). "Of note, systemic administration of arvanil (a synthetic, non‐pungent, blood–brain‐barrier permeable vanilloid) to mice harboring high‐grade gliomas decreased tumor size and extended survival of the animals, thus suggesting a therapeutic potential for TRPV1 agonists." (PMID 35322459, 2023). "Capsaicin and arvanil could activate TRPV1 to induce the glioma cell apoptosis via Ca2+‐entry and ER stress." (PMID 38093622, 2023). "This mtCB1R‐evoked process could operate in concert with AEA‐evoked anti‐glioma action, which relies on Ca2+ efflux from the ER upon TRPV1 engagement." (PMID 35322459, 2023). "Futhermore, neural precursor cells could migrate to the glioma cells in a distance and further induce the cell death of glioma cells by stimulating the TRPV1 channel." (PMID 38093622, 2023). "In GBM, these neural progenitor cells may be activated to migrate and interact with high-grade astrocytomas, release certain fatty-acid ethanolamide agonists to TRPV1, reduce glioma expansion, and prolong survival by stimulating tumour-supressed TRPV1." (PMID 36497400, 2022). "Conversely, the TRPV1 gene was significantly downregulated with glioma progression to GBM." (PMID 36497400, 2022). "Conversely, TRPV1 was significantly downregulated with increased glioma grade." (PMID 36497400, 2022). "For example, TRPV1 activation can reduce glioma expansion and prolong survival of glioma patients." (PMID 36304985, 2022). "This suggests that targeting and activating TRPA1 or targeting TRPV1 in glioma exhibiting such expression, can restore apoptotic signaling and might provide new insights for the development of alternative therapies against glioma progression." (PMID 33928077, 2021). "Commensurate with the tumour-suppressor capabilities of TRPV1, the expression of TRPV1 has been shown to be significantly decreased in the high-grade glioma, glioblastoma multiforme (GBM), thereby potentially reducing the therapeutic benefits of CBD in advanced patients." (PMID 32340151, 2020). "Furthermore, capsaicin belongs to the group of dietary phytochemicals demonstrating anticancer activity, and its action in glioma and urothelial cancer cells is shown to induce TRPV1-mediated, Ca2+-dependent apoptosis." (PMID 33613196, 2020). "Moreover, neural precursor cell stimulation of TRPV1 has been found to trigger high-grade glioma cell death, activating the ATF3 transcription factor controlling ER stress pathway." (PMID 27829230, 2016). "Moreover, the expression of 5'UTR TRPV1 variants in GBM, glioma stem-like cells (GSCs) and the 5'UTR TRPV1 variants role as prognostic factor in the survival of GBM patients have been evaluated." (PMID 27829230, 2016). "Moreover, TRPV1 is also involved in glioma progression and changes of its expression contribute to malignancy." (PMID 27829230, 2016). "TRPV1 may be downregulated by gliomas resulting in protection against apoptosis." (PMID 36768856, 2023). "Interestingly, authors demonstrated that protein expression of TRPV1 in the NK cell was comparable to PBMCs and U87 glioma cells, but was significantly lower from the expression level in the murine brain which confirms differences in the expression levels between different tissues." (PMID 31681615, 2019). "Additional research has demonstrated that in human glioma neurons, AEA and capsaicin together induce apoptosis, oxidative stress, and Ca2+ buildup via the TRPV1 channel." (PMID 38720772, 2024). "There is a growing consensus that TRPV1, TRPV2, TRPM2, TRPM3, and TRML1 exert anti-tumorigenic properties in glioma, while TRPC1, TRPC6, TRPM7, TRPM8, and TRPML2 promote glioma growth and proliferation." (PMID 36768856, 2023). "Several TRP channels have been studied as potential biological markers of glioma progression and prognosis, including TRPC1, TRPC6, TRPM2, TRPM3, TRPM7, TRPM8, TRPV1/2." (PMID 36768856, 2023).
glioma (continued). "Local anesthetic (e.g., lidocaine) upregulates the TRPV1 channels and suppresses the TRPM7 channels, and both of these mechanisms protect against glioma cell proliferation." (PMID 34389754, 2021). "First, TRPV1 and TRPV2 genes and protein expression appeared inversely correlated with glioma grade, showing an almost undetectable level in GBM." (PMID 33928077, 2021). "More specifically, TRPV1 and TRPV2 have revealed a protective role in glioma cells by regulating cell proliferation and survival, stem cell differentiation and sensitivity to drugs, whereas TRPV4 was found to increase cancer cell invasiveness." (PMID 33928077, 2021). "The activation of TRPV1 by CBD, and of TRPV2 by CBD and ∆9-THC, inhibits human glioma cell proliferation and viability in vitro." (PMID 32340151, 2020). "Considering that FXYD6 is a member of FXYD family and natural endogenous inhibitor of NKA, and could promote TRPV1 activity, therefore, we wondered about the possible role of FXYD6 in gliomas." (PMID 38093622, 2023). "Three major CNRs, highly specific CB1, less selective GPR55, and non-specific ion receptor protein TRPV1, are overexpressed in low-grade glioma and GBM vs. normal brain." (PMID 36497400, 2022). "CNR1 and GPR55 did not correlate with glioma grade, whereas TRPV1 negatively correlated with grade and positively correlated with longer overall survival." (PMID 36497400, 2022). "The relative expression of CNR1, GPR55 and TRPV1 genes in tissues showed that the three cannabinoid receptor genes did not correlate to each other in glioma or in GBM tissues, meaning they were independently regulated." (PMID 36497400, 2022). "Conversely to TRPV1 and TRPV2, TRPV4 has revealed a pivotal role in promoting glioma progression." (PMID 33928077, 2021). "The scientific literature reports the implications of TRPV1 and TRPV2 in glioma cell biology." (PMID 34458247, 2021). "Furthermore, we found that the TRPV1 variants expression levels strongly decreased in TRPV1 positive (TRPV1+) glioma samples (grade III and IV), except for the TRPV1v3, which expression was maintained in grade IV TRPV1+ samples." (PMID 27829230, 2016). "The Transient Receptor Potential Vanilloid type-1 (TRPV1) channel is a non-selective cation channel belonging to the Transient Receptor Potential family; variation of its expression has been correlated to glioma progression." (PMID 27829230, 2016). "In light of these data, the inverse correlation between TRPV1 expression and glioma grade from I to III and the reduced or lost TRPV1 expression found in GBM patients is most likely a mechanism by which tumor cells may evade anti-proliferative and pro-apoptotic signals." (PMID 33928077, 2021). "Upon exposure to low doses of the TRPV1 specific agonist capsaicin (CPS), the TRPV1-Ca2+ may sustain apoptosis in gliomas through the selective activation of p38 MAPK, but not ERK MAPK." (PMID 33928077, 2021). "In addition to TRPV1, TRPV2 plays a role in regulating glioma cell survival and proliferation, with high levels of TRPV2 expression detected in benign astrocytes, with progressively less expression of TRPV2 in high-grade gliomas corresponding with histological grade." (PMID 32340151, 2020). "For example, CBD’s effects in glioma are dependent on TRPV2, but not on CB1, CB2, and TRPV1." (PMID 33143283, 2020).